SOX2 (SRY-box transcription factor 2)
Diseases named in the same sentence as SOX2 in open-access papers (continued):
Sharing a sentence is not in itself a finding about the gene and the disease.
cancer (continued). "This reprogrammed metabolism-induced differentiation in the three types of cancer may involve the down-regulation of CSC TFs, such as OCT3/4, Nanog and SOX2." (PMID 30544833, 2018). "Moreover, FOXC1 knockdown decreased expression of Oct4, NANOG, SOX2 and ABCG2, which are important downstream target genes of beta-catenin in regulating cancer stemness." (PMID 30189871, 2018). "Since CD44 positivity represent stemness of a cancer cell line along with other markers such as OCT3/4, SOX2, KLF4, and Nanog, this approach may contribute to the retardation of tumor growth by restricting cancer stem cell population." (PMID 30619758, 2018). "BRACHYURY and SOX2 were not sufficient for initiation of cancer stem cell property, especially pluripotency related genes." (PMID 30453543, 2018). "In addition, SOX2, OCT4 and NANOG are transcription factors that play key roles in maintaining the pluripotency of embryonic stem cells and cancer stem cells." (PMID 29552304, 2018). "NANOG and OCT3/4 mRNA expression levels were significantly downregulated while that of SOX2 was upregulated in cancer compared to noncancer tissues." (PMID 29849920, 2018). "Similar induction was also observed in human mesenchymal stem cells (hMSCs), suggesting that the induction of Sox2 by nicotine is not restricted to cancer cells." (PMID 30322398, 2018). "OCT4, SOX2, NANOG, Krüppel-like factor 4 (KLF4) and c-MYC play a significant role in triggering pluripotency in somatic cells, and they have been used to identify CSC subpopulations within various types of cancer." (PMID 30177970, 2018). "Their synergistic effect, however, may be more crucial because the interaction of the SOX2 and BRACHYURY gene networks activates a vast network of genes/proteins that drives the development of cancer invasiveness." (PMID 30453543, 2018). "Nonetheless, CSCs are responsible for cancer cell metastasis, drug resistance, and tumor relapse, perturbing VEGFR2/STAT3/Myc/Sox2 axis might be useful in overcoming the chemo-resistance in triple-negative breast cancer." (PMID 29455658, 2018). "In order to further address the role of dedifferentiation of cancer cells after progranulin treatment, we used a GFP-Sox2 response reporter cell line (BioCat GmbH) and monitored the Sox2-expressing cells during progranulin treatment using the Operetta high-content imaging system." (PMID 30454027, 2018). "The well-known cancer target TF include MYC, the ETS family, STAT, Fos, Jun, Myb, Sox2 and more." (PMID 29970794, 2018). "We had previously shown that Yap1 was elevated in cancer stem-like cells from NSCLC and was necessary for their self-renewal and ability to form angiogenic tubules; and these effects of Yap1 were mediated through the induction of Sox2." (PMID 30322398, 2018). "Moreover, TGFβ1 was able to enhance the mRNA expression of Oct4, Nanog and Sox2 and drastically increased anchorage-independent colony formation in TGFβ1–sensitive NSCLC cells, suggesting the acquisition of cancer stem-like properties." (PMID 29995950, 2018). "In addition, we observed a notable inhibition of the markers of cancer stem cells such as OCT4, Sox2 and Nanog." (PMID 28380428, 2017).
cancer (continued). "The analysis showed that the three types of cancer cells (EA, EAintEMT and EAEMT) expressed SOX2, suggesting that cancer stem-like cells might become EMT cells." (PMID 29079795, 2017). "This study employed a candidate-based approach and the involvement of other potential NFATc2 and SOX2 targets in cancer phenotypes is not addressed." (PMID 28737489, 2017). "In our samples, no differential expression was observed between cancer and noncancer tissues; nevertheless, lower expression of SOX2 mRNA was correlated with cancer infiltration of renal pelvic tissues." (PMID 29104726, 2017). "SOX2 levels are elevated in primary tumors of patients who do not respond to endocrine therapy, and SOX2 has been reported to maintain stem cell subpopulations in various cancers." (PMID 28929082, 2017). "These lncRNAs could regulate the expression of CSC-related transcriptional factors, such as SOX2, OCT4, and NANOG, in colorectal, prostate, bladder, breast, liver, and other cancer types." (PMID 29299179, 2017). "Stem cell surface marker CD133 and stemness proteins OCT3/4, SOX2 expression levels were increased in A549/PTX CD133+ cells than in CD133- cells, indicating that the cancer stem cell-marker and stemness protein levels are significantly higher in A549/PTX CD133+ cells than in CD133- cells." (PMID 29299167, 2017). "Our results showed that sorted and expanded CD8+ CIK cells were activated by ovarian cells expressing OCT4 and Sox2, suggesting these CD8+ CIK cells may effectively target CSC of ovarian as well as other cancers." (PMID 28426690, 2017). "The SOX2 gene is amplified in several cancers, and SOX2 has been shown to be expressed in some tumors, but not in their surrounding tissue." (PMID 28388544, 2017). "Furthermore, the expression of cancer stem cell (CSC) markers CD44, CD133, Nanog and Sox2 were detected in neoplastic samples of these patients by immunohistochemistry." (PMID 28262804, 2017). "Our data also distinguish a different SOX2 enhancer region accessible to NFATc2 which functions not only in the presence of KRAS mutation (A549, PDCL#24) but also in EGFR mutant (HCC827) cancers." (PMID 28737489, 2017). "SOX-2 is a member of the SRY-related HMG-box (SOX) transcription factor family involved in several cellular processes, including maintenance of embryonic stem cells potency and differentiation of neural progenitor cells and cancer development." (PMID 28424427, 2017). "Interestingly, the GBM cell lines U87MG and U251 were found to express cancer stem cell markers CD133, NANOG, Oct4 and Sox2." (PMID 26983719, 2016). "Recently, a cohort of genes related to cancer pathways have been identified and validated as targeted genes of miR-145, such as P70S6K, C-MYC, PAI-1, FASCIN, and SOX-2, suggesting that miR-145 is an oncogene that plays a pivotal role in the initiation and progression of cancer." (PMID 27304058, 2016). "In addition to cell surface markers, several pathways and molecules that control self-renewal and differentiation of cancer stem cells and normal stem cells have been identified including p-STAT3, NOTCH, C-Myc, NANOG, OCT4, SOX2 and others." (PMID 27472461, 2016). "Increases in expression of the progenitor cell markers SOX2, SOX9 and NANOG in A549 cells seen in the present study could be indicative of the presence of such a cancer stem cell population." (PMID 27792742, 2016). "Overall, SOX2 represses cell cycle inhibitors and activates cell cycle accelerators; however, the pattern of gene regulation is not universal in different cancer cell types." (PMID 26846300, 2016). "Compared to parental cancer cells, spheroid cells overexpressed CD44, CD133, Oct4, Nanog, β-catenin, SOX2, Gli1 and p-ERK, which provided evidence for the existence of CSCs and suggested some of these markers might be used to identify gastric CSCs." (PMID 26769843, 2016).
cancer (continued). "Moreover, R182 cells showed enhanced levels of cancer stemness biomarkers such as OCT4, SOX2, CD44, and CD133, compared with the marginal expression of these factors in A2780 cells." (PMID 27708225, 2016). "BORIS-positive cells expressed cancer stem genes including CD44, ALDH1, NANOG, OCT4 and SOX2." (PMID 26849232, 2016). "However, five human lncRNAs which were previously reported to be cancer-related lncRNAs displayed high sequence conservation with NMR lncRNAs, especially the human lncRNA ENST00000493116 (also known as SOX2 overlapping transcript, SOX2OT)." (PMID 27833660, 2016). "Importantly, BORIS-silencing led to down-regulation of hTERT, stem cell (NANOG, OCT4, SOX2 and BMI1) and cancer stem cell markers (ABCG2, CD44 and ALDH1) genes." (PMID 26185996, 2015). "Accumulated evidence from various cancer types strongly support the hypothesis that hypoxia sustains the self-renewal characteristics of a portion of cancer cells in hypoxic niches mainly due to the upregulation of Oct4, NANOG, SOX2, Klf4, and c-myc." (PMID 26042045, 2015). "Additionally, we observed that DC120 suppressed the cancer stem-like SP cells through the inhibition of AKT kinase activity and the blockade of the PI3K/AKT downstream signaling pathway, further regulating Sox2 expression." (PMID 25749514, 2015). "Through unsupervised clustering in stage II cancers, we identified two cluster groups that are broadly defined by inflammatory or immune-related factors (CD3, CD8, COX-2 and FOXP3) and stem-like factors (CD44, LGR5, SOX2, OCT4)." (PMID 25906747, 2015). "With the exception of Myc (which was only present in a subset of benign, borderline, and malignant tumors), Oct4, Nanog, Sox2, and Klf4 were detectable at variable levels across both normal and diseased tissues." (PMID 26412983, 2015). "SOX2 is over-expressed in CRC tissues and regulates cancer cell growth in vitro and in vivo." (PMID 25868860, 2015). "Cancer stem cell markers including OCT4 and SOX2 have been found in various solid tumors." (PMID 26706028, 2015). "Therefore, using erlotinib to inhibitEGFR to kill the cancer cells increases the activity of FOXO6, which in turn promotesthe survival of some of the cells by activating the SOX2 gene." (PMID 25686219, 2015). "SOX2/livin pathway regulates CSC survival, so it could be targeting as an effective therapeutic strategy for cancer treatment." (PMID 28983346, 2015). "Cancer stem cells are molecularly characterized based on the expression of various cell surface receptors including integrin a6 (CD49f), integrin b1 (CD29), hyaluronan receptor (CD44), and the stem cell self-renewal transcription factors NANOG, OCT4, and SOX2." (PMID 26005638, 2015). "Expressions of cancer stemness-related genes such as Sox-2, and Nanog-1 but not Oct-4, were showed decreasing trend by carbon ion beam combined with gemcitabine compared to that of carbon ion beam, X-ray alone or X-ray combined with gemcitabine." (PMID 25849939, 2015). "The c-Met, Sox2 and Oct4 mRNA expressions in CD133+ cells were significantly higher than those in CD133− cells, which suggested that CD133+ cells have characteristics of cancer stem cells." (PMID 26391180, 2015). "Accordingly, cancer cells present some remarkable similarities with embryonic stem cells, including unlimited proliferation and self-renewal, and the expression of pluripotency genes, such as NANOG, OCT4 or SOX2." (PMID 26203771, 2015). "Moreover, the 3D growth microenvironment induced the cancer cells to express the reprogramming transcription factors OCT4, SOX2, NANOG and LIN28." (PMID 25883172, 2015). "It is likely that cross-regulation between cyclin D1 and Dicer might occur in other cancers, especially in ATC, which are enriched in SOX2 producing cells, which we suggest is part of the network." (PMID 25705224, 2015).
cancer (continued). "Taken together, SOX2 mediates self-renewal of CSCs through EGFR signaling in at least two cancer types and is a major mediator of self-renewal in several cancers through mechanisms that remain unclear." (PMID 25114775, 2014). "SOX2 has been described by others to enhance the migratory and invasive effect of CRC cells as wells as of other cancer cell types, which implies that SOX2 expressing cells might harbor a higher metastatic capacity." (PMID 25010701, 2014). "Aberrant expression of the transcription factor SOX2 has recently been observed in several cancer types, but its role in CRC has not been fully elucidated." (PMID 25010701, 2014). "While the functional importance of Sox2 in embryonic stem cells is well characterized, the biological significance of Sox2 in cancer has not been extensively studied." (PMID 24885403, 2014). "Although Sox2 expression has been found in several types of cancer, it has not yet been used to identify or isolate CSCs in somatic carcinoma." (PMID 24489842, 2014). "As a result, we have discovered that Sox2 does regulate an intriguing list of genes in the RR cells, but this does not exclude the possibility that other important cancer and/or stem cell genes exist in our ChIP-chip lists." (PMID 25380620, 2014). "Recently, it has also been shown that cancer cells expressing OCT4 and Sox2 may be crucial in cancer development." (PMID 25120646, 2014). "SOX2 and SOX9 both exhibited frequent over- and underexpression within the same cancer type, potentially indicating their dual roles in cancer and that they could be differentially selected for in cells with different genetic backgrounds." (PMID 25594027, 2014). "Moreover, the CD133+ cells showed characteristics consistent with CSC, namely neurospheres formation, expression of neural/cancer stem cell markers (CD133, Nestin, SOX-2) and differentiation marker (GFAP)." (PMID 24978848, 2014). "Cancer-specific survival analyses revealed that patients with SOX2 positive tumors had a poorer prognosis than patients with SOX2 negative tumors." (PMID 25010701, 2014). "Indeed, current evidence indicates some specific pluripotency genes, such as OCT4, SOX2 and NANOG, expressed in specific human cancer types as putative regulators of embryonic stem cell (ESC) identity." (PMID 25127259, 2014). "Mean SOX2 expression in SCC, INVC and SNUC was significantly higher in SOX2 amplified cancer samples (125±40) than in non-amplified tumors (80±33) (p<0.001)." (PMID 23544055, 2013). "The expression of Sox2 in a non-stem cell context without Nanog or Oct4 also raises critical questions about its epigenetic regulation within cancer." (PMID 23326489, 2013). "Reflecting a gene-dosage effect, SOX2 amplified carcinomas displayed a significantly higher SOX2 protein level than non-amplified carcinomas." (PMID 23544055, 2013). "Irrespective of the specific histology, patients with SOX2-amplified SCCs, SNUCs, and INVCs experienced a significantly higher incidence of recurrence (15/20; 75%) as opposed to non-amplified carcinomas (13/31; 42%) (p = 0.02)." (PMID 23544055, 2013). "Exposure of non-stem cancer cells to ionizing radiation enhanced spherogenesis, and this was accompanied by upregulation of the pluripotency genes Sox2 and Oct3/4." (PMID 22928007, 2012). "Several studies have suggested that the Sox2-Oct4 complex is essential for the transforming growth factor-β (TGF-β) and wnt/β-catenin pathways, which have emerged as other important players in the self-renewal and maintenance of cancer stem cells." (PMID 22837720, 2012). "In vitro experiments allowed to detect UTF1 in the nucleus of epithelial somatic cancer cell lines even in the absence of its main known regulators, Sox2 and Oct4A." (PMID 22880087, 2012). "Among over 20 cancer-related genes we investigated, only two showed changes in expression after SOX2 knockdown (data not shown)." (PMID 21304604, 2011).
cancer (continued). "Although the SOX2 response program in mouse stem cells was previously defined, the re-activation program in cancers such as GBM has not yet been defined." (PMID 21211035, 2011). "This region has cancer-related genes (PRKC1 and SOX2) as well as ECT2." (PMID 21124766, 2010). "Both pseudotyped lentiviral vectors transduced cancer stem-like cells characterized by their CD133-, nestin- and SOX2-expression, the ability to form spheroids in neural stem cell medium and to express astrocytic and neuronal differentiation markers under serum conditions." (PMID 19617915, 2009). "In cisplatin-resistant OSCC, TGF-β1 modulates the cancer cell stemness where it inhibited the tumor suppressor gene FOXO3a via AKT pathway, a non-canonical, SMAD-independent pathway, resulting in the increased expression of SOX2 and ABCG2, which are markers of stemness." (PMID 40176914, 2025). "We detected the expression levels of the stemness markers including OCT4, SOX2, and Nanog, finding that DUSP3 upregulation significantly decreased their expression levels; conversely, DUSP3 downregulation resulted in a noticeably higher levels of cancer stemness markers." (PMID 39744427, 2025). "All these findings which observed a strong positive expression of SOX2 transcription factor in OKC and Ab suggest that these lesions have cells with characteristics of cancer stem cells that could be related to the progression and recurrence of these aggressive odontogenic pathologies." (PMID 41176605, 2025). "By regulating the WNT inhibitor DKK1, SOX2 promotes a quiescent, immune-evasive state in LCC cells, illustrating how TFs interact with epigenetic changes (H3K27ac and Pol II binding) and cell signaling to influence cancer cell stemness, survival, and initiation of metastasis." (PMID 40016470, 2025). "Moreover, principal component analysis of single-cell RNA-sequencing data of 65,655 GSCs and 14,207 GBM cells revealed that the area where CYP3A5 was highly expressed harbored cells that also markedly expressed cancer stem cell markers, such as PROM1, SOX2, EZH2 and NOTCH1." (PMID 39754188, 2025). "Stemness-related genes have been found, such as SOX2 (sex-determining region Y-box 2), NANOG (Nanog homeobox), and OCT4 (octamer-binding protein 4), along with the expression of the surface markers CD133+ and CD44+ and chemokine markers such as CXCR4 on cancer stem cells as stemness markers." (PMID 39684461, 2024). "Previous studies have also reported that SOX-2 and E2F3 may promote the migration of cancer cells." (PMID 38864530, 2024). "This indicates that, the TOP2A may not regulate the cancer stem cell self-renewal function directly by regulating through Oct-4 and Sox2 rather it regulates by other mechanism." (PMID 38957610, 2024). "Ultimately, our findings demonstrate that SOX2 is not absolutely essential in LUAD cancer cells." (PMID 38334608, 2024). "Furthermore, we found that simultaneous activation of acetylation and inhibition of O-GlcNAcylation led to near-complete suppression of Sox2 in CRC cells, suggesting that the additive effects of these PTMs on Sox2 suppression might be used in cancer treatment." (PMID 38473392, 2024). "E2F3 interaction with SOX-2, altered its expression levels in TAM resistant cells, and its involvement in regulating pluripotency, differentiation of cancer stem cells (CSC), and the Wnt signaling pathway suggests that it might be involved in the emergence of TAM resistance." (PMID 38864530, 2024). "However, the question of whether SOX2 is necessary and sufficient in the RAB4A regulation of cancer stemness still needs to be addressed." (PMID 39463384, 2024). "Moreover, since a stem-like phenotype sustains cancer cell survival after detachment from ECM, we evaluated the expression of SOX2, OCT3/4, KFL4 and ALDH1 stemness markers and we found that p3 anoikis-resistant cells show a tendency to increase the expression of these markers, especially ALDH1." (PMID 39175551, 2024).